MIR4774 (microRNA 4774)
Synonyms: hsa-mir-4774
Gene: MicroRNA gene on chromosome 2 (168,582,943 to 168,583,018, forward strand). Ensembl gene ENSG00000265694.
Homologues: Orthologues: chimpanzee MIR4774 (100% identical).